MCL1 (MCL1 apoptosis regulator, BCL2 family member)
Diseases named in the same sentence as MCL1 in open-access papers (continued):
Sharing a sentence is not in itself a finding about the gene and the disease.
tumor (continued). "EGFR and Mcl-1 mRNA and protein expression levels were significantly higher in HNC tissues than in normal or margin tissues using datasets obtained from the Gene Expression Omnibus (GEO), the Cancer Genome Atlas (TCGA), and Clinical Proteomic Tumor Analysis Consortium (CPTAC)." (PMID 38888847, 2025). "MCL1, a member of the BCL-2 family, inhibits apoptosis by sequestering pro-apoptotic factors at the mitochondrial outer membrane, and its overexpression has been frequently observed in various human malignancies, contributing to tumor progression and therapeutic resistance." (PMID 41154579, 2025). "Moreover, our scRNA-seq analysis using human clinical specimens supported the idea that MCL1 is more highly expressed in non-tumor than in tumor cells, and our ST data also suggests that Mcl1 expression is not specific to tumors." (PMID 39122703, 2024). "Next, we further determined whether the ablation of Tsc2 alone could also accelerate c-MYC tumor development without MCL1." (PMID 39325536, 2024). "The combination of Venetoclax and HMAs may synergistically exert anti-tumor effects by upregulating the expression of pro-apoptotic proteins NOXA and PUMA, while inhibiting the activity of pro-survival proteins MCL1 and BCL-XL, thereby facilitating apoptosis in AML tumors." (PMID 39355240, 2024). "Therefore, if tumor cells overexpress BCL-xl and MCL-1, they are resistant to Venetoclax." (PMID 39060763, 2024). "However, BCL2L1 was highly expressed specifically in tumor cells, while MCL1 was expressed at lower levels in tumors compared to non-tumor cells." (PMID 39122703, 2024). "Given the safety concerns identified in clinical trials with MCL1 inhibitors, it appears particularly important to identify strategies in which low doses of an MCL1 inhibitor may be sufficient to sensitise tumour cells without unwanted toxicities." (PMID 37723317, 2023). "On this basis, we hypothesized that inhibiting Mcl-1 by NSC260594 could improve everolimus-induced apoptosis in TNBCs, and the combination of NSC260594 and everolimus could provide synergistic effects in tumor-killing activity." (PMID 37481672, 2023). "In this context, other BH3 mimetics such as ABT-737 and its oral derivative navitoclax, which bind to Bcl-2, Bcl-xL and Bcl-w (but not Mcl-1) with high affinity have also been investigated in MM, but their development was precluded either due to lack of anti-tumor activity or unacceptable toxicity." (PMID 36672426, 2023). "However, since venetoclax does not target Mcl-1 and Bcl-xL, it cannot block binding of Bim with them and thus impairs the anti-tumor activity of this agent." (PMID 37644011, 2023). "That MCL-1 antagonism is required for apoptosis mediated by BCL-XL inhibition was hinted at in early papers reporting the activity of ABT-737, where ABT-737 induced apoptosis only in tumours with low MCL-1 levels, and MCL-1 downregulation sensitised resistant cells." (PMID 37898609, 2023). "Thus, we hypothesized that drugs that activate PP2A could reverse venetoclax resistance via dephosphorylation of BCL-2, MCL-1, BAD, and BAX, thereby resensitizing tumor cells to BCL-2 inhibition." (PMID 37751299, 2023). "Furthermore, MCL1 silencing reversed resistant phenotypes against the cognate CTLs of CT26-Nanog cells, suggesting a crucial role of MCL1 in the tumor-intrinsic CTL resistance induced by NANOG." (PMID 35104240, 2022). "Distinct from these canonical functions, recent reports suggest the existence of some noncanonical functions of Mcl-1 that may further contribute to the survival of tumor cells." (PMID 36045907, 2022).
tumor (continued). "Interestingly, mono-therapeutic treatment with the MCL-1-specific BH3-mimetic VU661013 slowed the growth of HCC1187 and BT20 TNBC xenografts, and co-treatment with docetaxel or doxorubicin further enhanced the inhibition of tumor growth." (PMID 35349392, 2022). "Combining S63845 with docetaxel in two TNBC PDX mouse models, or trastuzumab in a HER2-amplified PDX mouse model, has been shown to significantly impair tumor growth and prolong survival, although monotherapy with the MCL-1 inhibitor failed to markedly prevent tumor growth." (PMID 35349392, 2022). "Thus, canonical and noncanonical prosurvival functions of Mcl-1 together support the growth of tumor cells, thereby further contributing to therapy resistance and poor prognosis." (PMID 36045907, 2022). "Moreover, treatment with the MCL-1-specific BH3-mimetic drug S63845 alone failed to overtly affect viability when tumour cell lines were maintained in 2D monolayers." (PMID 33785871, 2021). "To our surprise, the dramatic impact of loss or inhibition of MCL-1 in MMTV-PyMT tumours that we observed in vivo was not recapitulated in vitro with acute deletion of MCL-1 in cell lines derived from MMTV-PyMT primary tumours (hereafter referred to as tumour cell lines)." (PMID 33785871, 2021). "Thus, our results indicate that tumor cells sensitized by sirolimus become more dependent than normal cells on BCL2 and MCL1 for sustained survival, thus increasing their susceptibility to apoptosis in the absence of these key pro-survival proteins." (PMID 34331013, 2021). "The combined therapy could downregulate MCL-1 levels by suppressing the phosphorylation of STAT3; therefore, we sought to determine whether altering the expression of STAT3 in NPC cells would affect tumor cell apoptosis induced by APG-1252-M1 plus gemcitabine." (PMID 34354046, 2021). "However, the depletion of DCAF10 rescued the tumor suppression of ectopic OTUD1 expression in K244R mutant cells (comparing K244R&D1&shDCAF10 to K244R&D1), which is due to the inhibition of the MCL1 downregulation‐induced caspase‐dependent apoptosis pathway and AIF release (parthanatos)." (PMID 33898171, 2021). "The anti-apoptotic proteins Mcl1 and XIAP are known targets of CDK9, and suggests that CDK9 inhibition brings about its effects by suppressing anti-apoptotic or pro-survival signaling, while simultaneously activating pro-apoptotic and tumor-suppressive pathways." (PMID 34359807, 2021). "We found some indication (though the pattern is not as strong) that the effect of knocking out MCL1 or BCL-XL may also enhance the anti-tumor effect of FLT3 inhibition, though not to the same degree as with BCL2." (PMID 33076970, 2020). "The tumor-promoting effect of the absent HTATIP2 expression was associated with HIF2α upregulation and enhancement of c-Myc oncogenic activity through the HIF2α regulated β-catenin/c-Myc/MCL-1 pathway." (PMID 32545251, 2020). "However, little is known about the mechanism of how MCL-1 expression level is up-regulated and whether MCL-1 up-regulation plays an important role during tumor development process." (PMID 32802178, 2020). "Specifically, while tumors rapidly emerged in the liver parenchyma of c-Myc/MCL1 wild-type mice, resulting in high tumor burden by 5-6 weeks post hydrodynamic injection, a comparable tumor burden was observed only 36 weeks post injection in c-Myc/MCL1 mice depleted of FASN (c-Myc/MCL1/Cre mice)." (PMID 33187130, 2020). "Patients with highly expressing BCL-XL tumours had a non-significant, but strong trend towards inferior OS (11.8 versus 16.8 months) (HR 1.36, 95% CI 0.99–1.86, p = 0.057) but not high MCL-1 expression (13.5 versus 11.6 months) (HR 0.8, 95% CI 0.64–1.01, p = 0.064)." (PMID 33298868, 2020).
tumor (continued). "Ex vivo analyses of tumours, and in vitro studies on the MSTO-211H cells used in xenografts, showed induction of BH3-only proteins BIM and NOXA, which would account for the improved outcomes seen in the combination studies, as both of these proteins can potently inhibit MCL-1." (PMID 33298868, 2020). "It will also be interesting to see whether these outcomes can be further improved once more targeted BH3-mimetics (e.g. through conjugation to tumour-specific antibodies) are developed and which could potentially allow safe co-treatment with BCL-XL plus MCL-1 direct inhibitors." (PMID 33298868, 2020). "Therefore, MCL1 amplification, the TMN, and TNF-α, combined with clinical parameters including age, stage, maximum tumor dimension, brachytherapy schemes, and pretreatment hemoglobulin, were selected for the multivariate Cox regression model for survival analyses." (PMID 32527042, 2020). "Moreover, BETd-260 treatment augmented the expression of two typical apoptosis biomarkers, cleaved form of PARP, activated form of caspase-3 in HCC tumor tissue, suggesting that BET-PROTAC BETd-260 reciprocally modulates Mcl-1 and Bad, triggers apoptosis in HCC xenograft tumor tissues." (PMID 31993368, 2019). "Concerning the problem of improving the assessment of the anti-tumor activity of MCL-1 inhibitors, it is particularly interesting a recent study by Brennan and coworkers reporting the development of a humanized MCL-1 mouse strain in which murine MCL-1 was replaced with the human homolog." (PMID 30813354, 2019). "AZD5991 is a macrocycle inhibitor of MCL-1, with sub-nanomolar affinity for MCL-1 that induces apoptosis of leukemic cell lines and primary leukemic cells at nanomolar concentration in vitro and induces in vivo tumor regression in various mouse xenograft models." (PMID 30813354, 2019). "Tumour related survival, number of lung metastases, and other parameters of tumour development were all comparable between mice regardless of whether mice were bred to express mammary-specific deletion of Mcl1 or not." (PMID 29339815, 2018). "Verticillin A treatment decreased FLIP, Mcl-1, Bcl-x and increased Bak, Bax and Bim protein level in the tumor cells, resulting in activation of caspases, elevated cytochrome C release and increased apoptosis as determined by upregulated PARP cleavage in tumor cells." (PMID 29409480, 2018). "However, changes in MCL-1 expression are not involved in killing cSCC cells at low tumour-selective concentrations of pladienolide B." (PMID 29796170, 2018). "Importantly, immunohistochemical analysis on serial sections of RFP-positive areas of tumours from HOM mice revealed equivalent levels of MCL-1 protein to neighbouring cells that were RFP negative." (PMID 29339815, 2018). "The cell response to these agents is typically cytostatic allowing tumour cells to quickly adapt and acquire resistance; however, ERK1/2 inhibition increases the expression of multiple proapoptotic BOPs, thereby sensitising them to BH3‐mimetics targeting BCL‐XL and/or BCL2 or MCL1." (PMID 28548464, 2017). "Additionally, Bik was independent of anti-apoptotic Bcl-2, Bcl-xL, Mcl-1 and Bcl-w suggesting a complex mechanism of tumor promotion identified by Bik high tumors." (PMID 27120789, 2016). "Also, FBXW7, MCL1 and PLK1 may be relevant predictive markers of tumor progression and response to paclitaxel treatment." (PMID 27409838, 2016). "Loss of FBXW7 is associated with adverse prognostic factors such as tumor grade or non-luminal phenotypes and FBXW7, MCL1 and PLK1 levels may have predictive value in patients treated with paclitaxel." (PMID 27409838, 2016). "STAT3 activity supports tumour-cell survival by up regulating expression of the anti-apoptotic protein BCL-XL (B-cell lymphoma-2-like) and many other proteins involved in cell proliferation and survival including myeloid cell leukaemia 1 (MCL1), cyclin D1 and MYCC." (PMID 26186918, 2015).
tumor (continued). "In the absence of pro-apoptotic stimuli, Bim is sequestrated to Mcl-1 in tumor cells." (PMID 26405162, 2015). "Moreover, our analysis of tumor microenvironment both in our orthotopic tumors and in PTC clinical samples provides evidence that metastatic BRAFV600E-PTC with MCL1 and P16 copy number alterations are enriched with PDGFRB-positive stromal cells (i.e. pericyte)." (PMID 26636651, 2015). "sNEDD4 may regulate Mcl-1 and MMP9 to augment tumor invasion in a subgroup of patients." (PMID 25823820, 2015). "In this study, we examine the role of Mcl-1 in the resistance of GBM to TRAIL and identify R-roscovitine as a potential candidate drug that targets Mcl-1 to enhance the therapeutic effects of TRAIL in the treatment of TRAIL resistant GBM cells and in a 3D tumour model." (PMID 24213561, 2014). "The balance of Bcl-2/Mcl-1 proteins has also been largely shown to impact the efficacy of ABT-737, suggesting that modulation of Noxa and Mcl-1 could be used as a strategy for sensitizing tumor cells to ABT-737." (PMID 24454684, 2014). "The tumor suppressor activity of miR-29 may be achieved through targeting cell cycle regulators and oncogenes such as Cdk6, DNA methyltransferase 3A (DNM3A) and 3B (DNMT3B), Mcl-1, and Tcl1A." (PMID 23431463, 2013). "Some of the miRNAs with recently identified targets in vitro in various tumor settings other than GIST include: miR-132 targeting Rb1, miR-193b targeting CCND1 and Mcl-1, miR-455-3p targeting Smad2, miR-125b targeting Mcl-1 and Bcl-2 and miR-542-5p targeting survivin." (PMID 23717541, 2013). "Most strikingly, cell death was induced by Bcl-xL/Mcl-1 co-inhibition, however this was also observed in non-malignant cells indicating that this combination does not allow cell death induction in a tumor-specific manner." (PMID 22292048, 2012). "If the VEGF165-NRP1-c-MET pathway is required for Mcl-1 expression and survival in PCa cells, it would be intriguing to evaluate whether targeting NRP1 could interrupt both NRP1-c-MET signaling in tumor cells (survival) and NRP1-VEGF-Rs signaling in endothelial cells (angiogenesis)." (PMID 20085644, 2010). "Messenger RNA levels of Bax and of the antiapoptotic Bcl-xL and Bcl-2 (data not shown) did not change dramatically among all tumours tested, whereas Mcl-1 mRNA expression showed a small yet significant increase, but at a much lower level than the BH3-only Puma, Noxa and Bim-EL." (PMID 19455143, 2009). "In three typical cases tested, tumor cells were negative for MCL-1." (PMID 16563162, 2006). "Thus, while treatment with MRX-2843 combined with venetoclax or navitoclax provided robust anti-tumor activity in the studies reported here, the combined inhibition of BCL-XL, MCL1 and MERTK may provide even further improvement in therapeutic efficacy against EWS." (PMID 39199601, 2024). "Also, mTOR seems to differentially regulate MCL-1 in tumor and normal cells, therefore we could not see MCL-1 downregulation even after efficient mTOR inhibition in NHBE cells." (PMID 36588105, 2023). "Downregulation of Mcl-1 but not other antiapoptotic Bcl-2 family proteins potentiated the cell killing efficacy of these specific inhibitors, suggesting that regardless of the tumor lineage, the responsible oncoprotein or the corresponding targeted inhibitors, Mcl-1 was a common resistance factor." (PMID 36045907, 2022). "Since single treatment with MCL-1 inhibitors is effective in SCCL cell lines with high MCL-1 and low BCL-xL expression, we asked whether single BH3 mimetics directed against the most prevalent protein in a given TH or TC would be sufficient to induce anti-tumor activity." (PMID 34781947, 2021). "Without a cohort of primary tumor samples in patients who were confirmed to not have developed brain metastases to compare against it is impossible to make definitive statements, but this suggests that gain of MCL1 could be an early driver of metastasis." (PMID 34830758, 2021).
tumor (continued). "If this hypothesis is correct, one could predict that co-expression of an anti-apoptotic mediator, such as Mcl-1, would rescue TGFβ1 dependent tumor inhibition phenotype, i.e., overexpression of TGFβ1 would not be able to suppress tumor development induced by c-Myc and Mcl-1 oncogenes in the liver." (PMID 33608500, 2021). "MCL-1 also has reported non-canonical roles that may be relevant in its tumour-promoting effect." (PMID 33785871, 2021). "We further found that MARCH5 depletion increased MCL1 in multiple cell lines, indicating that MARCH5 plays a substantial role in regulating MCL1 under basal conditions, although this may still be NOXA-dependent and could reflect constitutive levels of stress in tumor cells." (PMID 32484436, 2020). "Hence, our data show that ALCL is a tumor that is dependent on TYK2 for cell survival, that TYK2 is activated through an autocrine loop involving IL-10 and IL-22, and that TYK2 promotes cell survival at least in part through activating the expression of the BCL2 family protein, MCL1." (PMID 30131584, 2019). "However, ABT-737 is not able to bind to Mcl-1, which results in tumor drug resistance." (PMID 31892356, 2019). "Interestingly when end-stage tumours were harvested, MCL-1 expression had recovered, which reinforces that MCL-1 inhibition transiently during early tumour development can still impact on tumour growth but that selection for presence of MCL-1 ultimately occurs." (PMID 29339815, 2018). "Efficacy, as measured by tumor growth inhibition (TGI) was assessed in 3 models of ABC (U2932, RIVA, and OCI-LY10) and two models of GCB (SU-DHL-4 and NU-DHL-1) subtype DLBCL to make an initial assessment of whether response to BCL-2/MCL-1 inhibition can be predicted based on genetic subtyping." (PMID 29269870, 2017). "However, unlike other tumor cell contexts, where suppression of mTORC1 has been shown to reduce MCL-1 expression, our analysis of GCB-DLBCL cells reveals an unpredicted mechanism of synergy wherein suppression of AKT induces mitochondrial accumulation of BAD and BIM." (PMID 26460954, 2015). "However, it is not clear why reduced Mcl-1 degradation through one pathway provides a substantial advantage to tumor cells, since multiple alternative pathways can target Mcl-1 degradation and might be expected to provide at least partial compensation." (PMID 23056582, 2012). "To avoid potential side effects, we suggested the alternative use of DT2216, a PROTAC targeting BCL-xL for degradation in tumor cells but not in platelets, and dinaciclib, a CDK9 inhibitor that potently suppresses MCL-1." (PMID 40113795, 2025). "As expected, although the single inhibition of BCLXL (by sgBCLXL) or MCL1 (by MCL1 inhibitor) did not affect the growth of HGC-27 xenografts, co-targeting BCLXL and MCL1 led to a substantial suppression of tumor growth in vivo." (PMID 40075071, 2025). "In our analysis, we found that MDSCs coexpressed high levels MCL1 and BCL2A1, but not any of the other populations of tumor-infiltrating myeloid cells captured in our analysis." (PMID 38459020, 2024). "In tumours where the MCL-1 level is low and MCL-1 is absent or inactivated, ABT-737 has a significant effect as monotherapy, but ABT-737 monotherapy is not effective in tumours with high MCL-1 expression." (PMID 35598030, 2022). "Additional evidence highlights that the anti-tumour effects of YM155 are not solely mediated by its modulation of Survivin, but also via its transcriptional downregulation of MCL-1 and induction of DNA damage." (PMID 35568716, 2022). "MCL-1 and BCL-XL are crucial for the survival of not only tumour cells, but also for non-malignant cells." (PMID 35201512, 2022).